CDH1 (cadherin 1)
Diseases named in the same sentence as CDH1 in open-access papers (continued):
Sharing a sentence is not in itself a finding about the gene and the disease.
hereditary diffuse gastric cancer (continued). "Hereditary diffuse gastric cancer (HDGC) confers autosomal-dominant genetic susceptibility to cancer syndrome, among which approximately 40% are caused by pathogenic mutations of CDH1." (PMID 37158533, 2023). "The E-cadherin gene, CDH1, and the α-E-catenin gene, CTNNA1, were previously identified as hereditary diffuse gastric cancer (HDGC) susceptibility genes, explaining 25% to 50% of HDGC cases." (PMID 36484990, 2022). "Patients with evidence of a CDH1 mutation or patients who meet the IGCLC criteria and who are diagnosed with diffuse gastric cancer should be treated in accordance with the international guidelines." (PMID 35448173, 2022). "Hereditary diffuse gastric cancer (HDGC) is a cancer syndrome caused by germline variants in CDH1, the gene encoding the EMT marker E-cadherin, but the mechanisms through which CDH1 loss initiates HDGC have not been determined." (PMID 34745998, 2021). "Hereditary diffuse gastric cancer (HDGC) is an autosomal dominant cancer syndrome defined by germline CDH1 or, occasionally, CTNNA1 variants in either an isolated individual with diffuse gastric cancer (DGC), or in a family with one or more cases." (PMID 35008338, 2021). "This is where the observational studies will help us understand more about non-CDH1 carriers developing diffuse gastric cancer." (PMID 33062523, 2020). "CDH1 germline pathogenic mutations cause hereditary diffuse gastric cancer syndrome (HDGC)." (PMID 30895400, 2019). "Germline mutations in the gene CDH1, encoding the cell adhesion protein E-cadherin, are causative of the autosomal dominant cancer predisposition syndrome Hereditary Diffuse Gastric Cancer (HDGC)." (PMID 29589180, 2019). "Notably, germline CDH1 c.88C>A has been reported in lobular breast and diffuse gastric cancer patients, as well as two unrelated individuals with cleft lip with or without cleft palate, a developmental birth defect that is known to be overrepresented in CDH1 mutation carriers." (PMID 29589180, 2019). "Our findings suggest that, ideally, clinical germline CDH1 testing should be incorporated into standard care for all Māori who present with early-onset diffuse gastric cancer." (PMID 29589180, 2019). "Disease-causing germline mutations in CDH1 cause Hereditary Diffuse Gastric Cancer (HDGC)." (PMID 27880784, 2016). "Personal or familial history of diffuse gastric cancer, above all at young age, should encourage CDH1 genetic testing." (PMID 27512640, 2016). "The correlation between an E-cadherin gene germline mutation (CDH1 inactivation) and the predisposition to diffuse gastric cancer was first identified in a large family in New Zealand." (PMID 25180051, 2014). "Mutations in the E-cadherin gene, CDH1, account for 40% of the most common form of familial gastric cancer (FGC), hereditary diffuse gastric cancer (HDGC)." (PMID 25340522, 2014). "Hereditary diffuse gastric cancer (HDGC) is a rare, inherited cancer syndrome with at least one fourth of HDGC patients having an autosomal dominantly inherited mutation of CDH1 (E-Cadherin)." (PMID 21331337, 2011). "Cases of hereditary diffuse gastric cancer diagnosed in the early stage during screening endoscopy without prior knowledge of CDH1 genetic mutation." (PMID 39895902, 2025). "In addition, hereditary diffuse gastric cancer (HDGC) is a subset of familial cancer syndromes, specifically associated with germline mutations to the E-cadherin (CDH1) gene." (PMID 41517275, 2025). "Germline pathogenic or likely pathogenic (P/LP) variants in the CDH1 gene, which encodes E-cadherin, lead to the Diffuse Gastric and Lobular Breast Cancer (DGLBC, formerly hereditary diffuse gastric cancer, HDGC [MIM: 137215]) syndrome with an autosomal dominant pattern of inheritance." (PMID 36246616, 2022).
hereditary diffuse gastric cancer (continued). "Analysis of the SCS data from mice with hereditary diffuse gastric cancer (HDGC) revealed that inactivation of Cdh1 led to metastasis along the squamous cell differentiation trajectory associated with aberrant expression of GI epithelial differentiation center genes." (PMID 35785171, 2022). "The majority of LBCs have negative immunohistochemical staining for E-cadherin (CDH1) expression, and the loss of CDH1 function was traditionally implicated in the tumorigenesis of diffuse gastric cancer as well as LBC." (PMID 35686104, 2022). "Germline alterations in CDH1 are seen in Hereditary Diffuse Gastric Cancer." (PMID 34680387, 2021). "The two families with a nonsense mutation and a splicing mutation in CDH1, respectively, did not have a family history of diffuse gastric cancer." (PMID 31892987, 2020). "Although CDH1 is the most relevant gene, explaining about 40% of the cases, other genes may be involved in familial gastric cancer." (PMID 30895400, 2019). "Together, combined comparative gene expression profiling and qHTS in patient-derived hereditary c.1380delA CDH1 SB.mhdgc-1 cells may open new avenues to improved individualized treatment options for familial gastric cancer." (PMID 28460635, 2017). "Clinically, patients with advanced familial gastric cancer and a genetic loss of CDH1 have a worse clinical outcome compared to patients with epigenetic silencing or no CDH1 alteration." (PMID 28460635, 2017). "The first family carries a novel truncating, nonsense CDH1 mutation that we were able to trace for three generations, but reports no family history of diffuse gastric cancer." (PMID 27064202, 2016). "Hereditary diffuse gastric cancer (HDGC) is a significant genetic predisposition syndrome, primarily caused by germline mutations in the CDH1 gene, which encodes the E-cadherin protein - a critical component for cell adhesion and tissue integrity." (PMID 40585607, 2025). "Germline mutations in CDH1 have been documented in several patients with early-onset diffuse gastric cancer (EODGC) without a family history, but the true incidence in this case is unknown." (PMID 39335135, 2024). "Therefore, in the absence of diffuse gastric cancer, germline genetic testing for CDH1 mutations is recommended for individuals in the setting of early-onset ILC (age < 45 years), bilateral ILC (age <70 years), or extensive family history of ILC1,2,8." (PMID 37758801, 2023). "Moreover, little is known on the risk of disease in carriers of a pathogenic CDH1 mutation in the absence of a family history for diffuse gastric cancer but with familial lobular breast carcinoma (HLBC)." (PMID 35448173, 2022). "However, in recent studies of individuals with pathogenic CDH1 variants, the family history was not a reliable determinant of the diffuse gastric cancer risk, making a sound recommendation difficult." (PMID 33929593, 2021). "The aim of this study was to uncover the pathogenic relevance and the underlying molecular mechanism of a novel CDH1 variant found in a Hereditary Diffuse Gastric Cancer family (p.L13_L15del), which affects the signal peptide of E-cadherin without changing the remaining predicted sequence." (PMID 30068367, 2018). "Hereditary diffuse gastric cancer (HDGC) is a rare malignancy, characterized by early-onset, highly-penetrant autosomal dominant inheritance mainly of the germline alterations in the E-cadherin gene (CDH1) and β-catenin (CTNNA1)." (PMID 36556253, 2022). "The genetic hallmark of HLBC is the CDH1 gene, and in female carriers, LBC is typically the first phenotype manifestation, even in the absence of diffuse gastric cancer (DGC)." (PMID 40366456, 2025). "Despite the strong correlation between CDH1 mutations and HLBC, the absence of diffuse gastric cancer in many patients presents diagnostic challenges." (PMID 40366456, 2025).
hereditary diffuse gastric cancer (continued). "Although based on a limited number of families requiring confirmation in larger cohorts, our data provide evidence that this list may be extended to the hereditary diffuse gastric cancer (HDGC) syndrome and the CDH1 gene." (PMID 33929593, 2021). "To address the lack of targeted molecular therapies for hereditary diffuse gastric cancer, we have utilized a synthetic lethal approach to identify candidate compounds that can specifically kill CDH1-null cells." (PMID 35008266, 2021). "We ascertained a large family from Maritime Canada with a history of Familial Gastric Cancer (FGC) displaying an apparent autosomal dominant pattern of inheritance, but bearing no variants in the coding region of the CDH1 gene." (PMID 25340522, 2014).
endometrial cancer (108 papers, 2000 to 2025). Primary or metastatic malignant neoplasm involving the endometrium (mucous membrane that lines the endometrial cavity). "The deletion of epithelial cadherin (Cdh1) or the tumor suppressor liver kinase B1 (Lkb1) along with Pten increases the severity of endometrial cancer invasiveness in mice." (PMID 40227710, 2025). "BMI-1 inhibition impacts on genes involved in SNAIL, SLUG, and CDH1 and reduces endometrial cancer cells’ migratory and invasive potential." (PMID 36497428, 2022). "Hypermethylated CDH1 promoter and repressed CDH1 expression were reported in some endometrial cancer cases." (PMID 25286960, 2014). "Because CDH1 mRNA is markedly upregulated in the early stages of tumor development of some types of tumors, such as colon and endometrial carcinomas, CDH1 mRNA levels may serve as a reliable biomarker for the early diagnosis of these carcinomas." (PMID 37189027, 2023). "CDH1 mRNA levels may serve as a reliable biomarker for the diagnosis of some tumors (such as colon and endometrial carcinomas) due to the marked upregulation of CDH1 mRNA in the early stages of tumor development of these carcinomas." (PMID 37189027, 2023). "Our results showed that in both endometrial cancer cells BMI-1 may be involved in EMT because inhibition of BMI-1 by PTC-209 caused a decrease in SNAIL and SLUG expressions and an increase in CDH1." (PMID 36497428, 2022). "Other interesting findings from the NGTS were: (i) frequent detection of RNF43 mutations in both dVIN and de-VIL, which have been previously associated with endometrial carcinoma, and (ii) detection of mutations in KEAP1, CDH1, PIK3R1, and POLE exclusively in de-VIL." (PMID 33918187, 2021). "Thus, we investigated whether expression of SESN2 correlates with that of the EMT markers, including CDH1 (encoding E-cadherin) and CDH2 (encoding N-cadherin), in the same dataset of endometrial cancer patients." (PMID 32899752, 2020). "However, the methylation pattern of CDH1 seems to be much more complex in endometrial cancer." (PMID 25286960, 2014). "In endometrial cancers, SNAIL and SLUG play a significant role in EMT because they inhibit the expression of the E-cadherin gene (CDH1)." (PMID 36497428, 2022). "Hypermethylation of APC, CHFR, Sprouty 2, RASSF1A, GPR54, CDH1 and RSK4 DNA and aberrant methylation of the mismatch repair gene hMLH1 in the endometrium are thought to be involved in the development of endometrial cancer." (PMID 23291663, 2013). "Reduced expression of genes such as APC, CHFR, Sprouty 2, RASSF1A, GPR54, CDH1, and RSK4 through a similar mechanism of hypermethylation has also been found in endometrial cancer." (PMID 22548175, 2012).
squamous cell carcinoma (98 papers, 1997 to 2025). A carcinoma arising from squamous epithelial cells. "Hypermethylation of this gene is more frequent in invasive forms of SCC compared to AK and normal population.Hypermethylation of CDH1 gene promoter is present in 95% of cutaneous squamous cell carcinoma samples." (PMID 37047618, 2023). "We detected CDH1 hypermethylation frequency of 100% in bladder UCs, squamous cell carcinomas and adenocarcinomas samples, as well as in normal adjacent urinary bladder tissue and in exfoliated urothelial cells from cancer-free controls." (PMID 18702824, 2008). "Also, it has been reported that ERα is able to induce fibronectin and inhibit CDH1 expression in squamous cell carcinoma to facilitate the EMT process." (PMID 35178360, 2021). "Methylation of CALCA, CDH1, DAPK1, and EVX2 was more common in squamous cell carcinomas (SCC) compared to adenocarcinomas (ADC)." (PMID 21507233, 2011).
liver cancer (96 papers, 2011 to 2025). An epithelial or non-epithelial malignant neoplasm that arises from the liver. "In in vitro models of liver cancer cell lines, the downregulation of miR-129-3p was associated with a reduced expression of epithelial markers (Cadherin 1 [CDH1] and CTNNB1) and an increase in mesenchymal markers (Cadherin 2 [CDH2] and Vimentin [VIM]))." (PMID 39598228, 2024). "Taken together, our study identified a novel microRNA signaling pathway, consisting of miR-9, PPARA and CDH1 that is deregulated in HCC patients affecting liver cancer cellular invasiveness." (PMID 26206264, 2015). "Therefore, to investigate the correlation between each NFYA variant and PCK1 in 297 liver cancers using RNA-seq data from TCGA, we classified by the logFC of VIM/CDH1 into two groups: those predominantly expressing NFYAv1 (1 < logFC) and those predominantly expressing NFYAv2 (logFC < −1)." (PMID 36092708, 2022). "By analyzing risk assessment using the TCGA-Liver-Cancer patient dataset (422 HCC patient samples) we confirmed that high expression of PD-L1 and mesenchymal marker VIM and low expression of epithelial marker CDH1 genes significantly associated with a high-risk signature (p < 0.05)." (PMID 30057891, 2018). "TRERNA1 is also upregulated in liver cancer, and reduces the H3K9 methylation of the promoter region of CDH1 genes to regulate the EHMT2/SNAI1 complex, resulting in the increased tumor metastasis." (PMID 35034562, 2022). "Overexpression of miR-9 suppressed significantly CDH1 mRNA levels, while inhibition of miR-9 expression by an antisense-miR-9 resulted in up-regulated of CDH1 mRNA levels, in both SNU-449 and HepG2 liver cancer cells, assessed by qPCR analysis." (PMID 26206264, 2015). "Therefore, our study provides a new insight about the expression pattern of Cdh1 and PAH in liver cancer tissues indicating its possible role in the progression of HCC." (PMID 33260674, 2020). "The mRNA expression levels of DEFB1 and CDH1 were positively correlated in GSE25097 (r = 0.354, P < 0.001), GSE14520 (r = 0.348, P < 0.001) and GSE36376 (r = 0.381, P < 0.001) liver cancer patient cohorts." (PMID 29042578, 2017). "Although the mechanism has not been fully elucidated, the identification of CDH1, E-cadherin, as one of the top co-regulated genes with β-defensin 1 consistently in 3 independent liver dataset has shed light on the role of β-defensin 1 in liver cancer." (PMID 29042578, 2017).
renal fibrosis (92 papers, 2011 to 2025). A final common manifestation of a wide variety of chronic kidney diseases characterized by glomerulosclerosis and tubulointerstitial fibrosis. "Additionally, we also observed that the expression of α-SMA, CTGF, and cdh1, which are involved in the apelin signaling pathway, was associated with renal fibrosis, leading us to speculate that this pathway may play an important role in the process of pulmonary fibrosis." (PMID 33176882, 2020). "Next, renal fibrosis markers were assessed, including COL1A1, VIM, CDH1, and ACTA2." (PMID 32854194, 2020).
oral cancer (89 papers, 2004 to 2025). "The meta-analysis of the gene promoter hypermethylation in oral cancer, that included 29 studies of which 13 were about CDH1 methylation, showed a significant correlation of CDH1 hypermethylation with oral cancer risk." (PMID 32961999, 2020). "A meta-analysis studied the relative frequency of CDH1 gene methylation—encoding E-cadherin—in oral cancer, demonstrating that this epigenetic mechanism may be involved in the loss of expression of this relevant adhesion molecule." (PMID 35954497, 2022). "Similarly, transcription factor Forkhead Box protein A2 (FOXA2) binding to the CDH1 promoter caused a high expression of E-cadherin and reduced cancer cell migration in oral cancer." (PMID 35563709, 2022). "A meta-analysis based on 13 studies revealed that increased methylation of the promoter of CDH1 is associated with oral cancer risk, and it has been suggested that this hypermethylation is associated with lower expression of E-cadherin protein in OSCC patients." (PMID 31712935, 2020). "Overall, we report frequent changes in tissue ultrastructure and gene hypermethylation of CDKN2A and CDH1 in oral cancer." (PMID 24782031, 2014). "In oral cancer, increased levels of HDACs are related to the repression of important tumor suppressor genes such as CDKN1A and CDH1." (PMID 40723400, 2025). "CDH1, one of the top hub genes, regulates the process of EMT in oral cancers via multiple pathways including the Wnt/β-catenin signalling cascade." (PMID 37316916, 2023). "Among these, HIF1α, CDH1, CD44, EGFR, and CCND1 were identified as the top hub genes that have also been reported as driver candidates responsible for oral cancer initiation and progression." (PMID 37316916, 2023). "Increased CDH1 and reduced CDH2 and VIM levels support the beneficial effect of ELLB in inhibiting cell migration and EMT in oral cancer cells." (PMID 36761830, 2022). "Additionally, CDH1 involvement in the EMT process, impacting the proliferation, invasion, and sensitivity to cisplatin in oral cancer cells." (PMID 41368332, 2025). "In oral cancer, the genes CDKN2A, APC, MGMT, PTEN, and CDH1 are frequently hypermethylated." (PMID 40723400, 2025). "It even reduced the phosphorylation of ERK1/2 and AKT1 with concomitant downregulation of cyclin D1 (CCND1), cadherin 2 (CDH2), and vimentin (VIM) and upregulation of cadherin 1 (CDH1) expression suggesting its anti-proliferative and anti-EMT effects in oral cancer." (PMID 36761830, 2022). "Increased promoter methylation for APC has been reported in clinical oral cancer tissues and some data do suggest a relationship between APC methylation status and development of lymph node metastases when it is analyzed in concert with the promoter methylation status of CDH1." (PMID 22645611, 2012).